PMEPA1 (prostate transmembrane protein, androgen induced 1)
Description:
Functions as a negative regulator of TGF-beta signaling and thereby probably plays a role in cell proliferation, differentiation, apoptosis, motility, extracellular matrix production and immunosuppression. In the canonical TGF-beta pathway, ZFYVE9/SARA recruits the intracellular signal transducer and transcriptional modulators SMAD2 and SMAD3 to the TGF-beta receptor. Phosphorylated by the receptor, SMAD2 and SMAD3 then form a heteromeric complex with SMAD4 that translocates to the nucleus to regulate transcription. Through interaction with SMAD2 and SMAD3, LDLRAD4 may compete with ZFYVE9 and SMAD4 and prevent propagation of the intracellular signal. Also involved in down-regulation of the androgen receptor (AR), enhancing ubiquitination and proteasome-mediated degradation of AR, probably by recruiting NEDD4.
Synonyms: STAG1; TMEPAI
Tractability: Antibody: its Gene Ontology location is reachable by antibodies, with high confidence; UniProt predicts a signal peptide or a membrane-spanning region.
Gene: Protein-coding gene on chromosome 20 (57,648,392 to 57,711,536, reverse strand). Ensembl gene ENSG00000124225.
Subcellular location: Early endosome membrane; Golgi apparatus membrane
Subcellular location (Human Protein Atlas): Vesicles
Pathways (Reactome):
Signal Transduction: Downregulation of TGF-beta receptor signaling
Gene Ontology:
Molecular function: protein binding; protein sequestering activity; R-SMAD binding; WW domain binding
Biological process: negative regulation of SMAD protein signal transduction; negative regulation of transforming growth factor beta receptor signaling pathway; androgen receptor signaling pathway
Cellular component: early endosome membrane; endosome membrane; Golgi membrane; membrane; plasma membrane
Genetic constraint (gnomAD): Loss-of-function variants: 7 observed, 16.55 expected, observed/expected ratio (o/e) 0.42, 90% interval 0.24 to 0.79. The synonymous counts are far from expectation, so gnomAD's model fits this gene poorly and the ratio says little. Missense variants: 354 observed, 347.98 expected, observed/expected ratio (o/e) 1.02, 90% interval 0.93 to 1.11. Synonymous variants: 193 observed, 150.03 expected, observed/expected ratio (o/e) 1.29, 90% interval 1.14 to 1.45.
Homologues: Orthologues: chimpanzee PMEPA1 (99% identical), macaque PMEPA1 (99% identical), dog PMEPA1 (94% identical), pig PMEPA1 (93% identical), mouse Pmepa1 (87% identical), rat Pmepa1 (87% identical), guinea pig PMEPA1 (79% identical), tropical clawed frog pmepa1 (75% identical), rabbit PMEPA1 (53% identical), Drosophila melanogaster CG5151 (23% identical). Paralogues in human: LDLRAD4 (62% identical).
Diseases named in the same sentence as PMEPA1 in open-access papers:
PMEPA1 is named in the same sentence as 56 diseases in open-access papers, as found by Europe PMC text mining. Sharing a sentence is not in itself a finding about the gene and the disease. The quoted sentences say what the papers report.
prostate carcinoma (25 papers, 2008 to 2026). A carcinoma that arises from epithelial cells of the prostate gland. "PMEPA1 is a gene associated with prostate cancer and other types of cancer, while TIMP1 encodes a metalloproteinase inhibitor." (PMID 40244296, 2025). "This study has also indicated that low expression of PMEPA1 is associated with poor prognosis in breast and prostate cancer and can serve as a prognostic marker for bone metastases." (PMID 34827641, 2021). "Our previous study had revealed that loss or reduced expression of PMEPA1 (isoform -b) was significantly associated with higher PSA level at diagnosis in prostate cancer patients." (PMID 32842649, 2020). "Further, a recent study showed that the loss of membrane-anchored PMEPA1 protein facilitated metastasis of prostate cancer via activating TGF-β signaling by sequestering SMAD2/3 in proteasome independent way." (PMID 32064040, 2020). "Hence, PMEPA1 isoforms (a, b and d) were implicated to be involved in mediating metastasis of prostate cancer." (PMID 32842649, 2020). "In this review, we aim to summarize the most recent advances in understanding of PMEPA1 isoform-specific functions and their associations with prostate cancer progression, highlighting the potentials as biomarker and therapeutic target in prostate cancer." (PMID 32842649, 2020). "The supportive role of PMEPA1 was demonstrated on a prostate cancer model, where low levels of PMEPA1 correlated with low metastasis-free survival." (PMID 40649997, 2025). "PMEPA1 is an androgen-responsive gene initially studied in the context of prostate cancer androgen-regulated gene networks." (PMID 40244296, 2025). "PMEPA1 specifically inhibits AR signal transduction, thereby suppressing the proliferation and colony formation of androgen-responsive prostate cancer cells." (PMID 39607204, 2024). "Some researchers have reported that silencing PMEPA1 can activate the androgen pathway, thereby accelerating the progression of prostate cancer." (PMID 39607204, 2024). "The inhibitory mechanisms of TGF-β signaling involved in PMEPA1 in prostate cancer are mainly applicable to subtype-a." (PMID 38173834, 2023). "While PMEPA1 isoforms a and d are the main isoforms that inhibit TGF-β signaling, the main isoform that inhibits AR signaling in prostate cancer cells is PMEPA1-b." (PMID 38173834, 2023). "Prostate transmembrane androgen inducible protein 1 (PMEPA1) can promote or inhibit prostate cancer cell growth based on the cancer cell response to the androgen receptor (AR)." (PMID 38173834, 2023). "Prostate transmembrane protein androgen induced 1 (PMEPA1) is a negative regulator of TGFβ signalling in prostate cancer cells." (PMID 35689009, 2022). "Reduced PMEPA1 (isoform -b) expression leads to up-regulated AR protein, activation of AR signaling, and subsequent accelerated prostate cancer cell growth." (PMID 32842649, 2020). "Our earlier study revealed that PMEPA1 inhibited the growth of both hormone dependent and independent prostate cancer cells." (PMID 32064040, 2020). "Through RNA Seq technology for unbiased detection of transcripts, we comprehensively analyzed PMEPA1 gene isoforms in androgen responsive VCaP, LNCaP prostate cancer cell lines and TCGA dataset of primary prostate tumor tissues." (PMID 32064040, 2020). "We analyzed the structures, expressions, biological functions and clinical relevance of PMEPA1-e isoform and less characterized isoforms c and d in the context of prostate cancer and AR/TGF-β signaling." (PMID 32064040, 2020). "Although our research has revealed the strong correlation of abnormal transcript levels of PEMPA1 isoforms (PMEPA1-a and PMEPA1-b) to aggressive prostate cancer outcome, the larger cohort still needs to validate these findings." (PMID 32842649, 2020). "Currently, 5 PMEPA1 isoforms (a, b, c, d, and e) are identified with distinct expression and function pattern in prostate cancer." (PMID 32842649, 2020).
prostate carcinoma (continued). "It was shown that the methylation of PMEPA1 gene promoter accounted for the silencing of PMEPA1 in prostate cancer cells in vitro and in vivo." (PMID 32064040, 2020). "Assessments of relative expression of each isoform indicated that PMEPA1-a was most abundant followed by PMEPA1-b and PMEPA1-c in prostate cancer cell lines and human prostate tumor tissues which are defined as major isoforms." (PMID 32842649, 2020). "The identification of prostate transmembrane protein androgen induced 1 (PMEPA1), an androgen responsive gene, came initially from the studies of androgen regulatory gene networks in prostate cancer." (PMID 32842649, 2020). "Towards this, the androgen dependent prostate cancer cell line LNCaP cells were used to assess the impacts of PMEPA1 isoforms (c, d and e) on androgen signaling and cell growth, cell plating efficiency and colony formation capacity in soft agar." (PMID 32064040, 2020). "Isoform PMEPA1-e was androgen responsive, consistent with the observations that PMEPA1-e was only detectable in AR positive prostate cancer cells." (PMID 32064040, 2020). "Nevertheless, the roles of other PMEPA1 isoforms (c, d and e) in the context of AR signaling were not fully understood in prostate cancer cells." (PMID 32064040, 2020). "To identify transcriptomic biomarkers for prostate cancer prognosis, we used TCGA dataset to test the clinical relevance and significance of PMEPA1 isoforms (d and e)." (PMID 32064040, 2020). "Expectedly, the high frequency of methylation of PMEPA1 gene was detected in prostate cancer frozen tissue samples which is also highly correlated to reduced expression of PMEPA1." (PMID 32842649, 2020). "The study utilizing PC-3 cells also confirmed the anti-metastasis function of PMEPA1 gene in prostate cancer cells via inhibiting TGF-β signaling." (PMID 32842649, 2020). "Evaluation of PMEPA1 isoforms c, d and e revealed a potentially new mechanism of prostate cancer cell adaptation from androgen dependent to TGF-β dependent cell growth." (PMID 32064040, 2020). "By screening for TGFβ-regulated genes in prostate cancer cells, the most highly upregulated gene found was PMEPA1 (prostate transmembrane protein androgen induced-1)." (PMID 30463358, 2018). "In this regard, it has been recently shown that the TGF-β signaling regulator PMEPA1 suppresses prostate cancer metastases to bone." (PMID 27662660, 2016). "Thus, we have demonstrated that PMEPA1 is hyperexpressed when MSCs co-cultured with prostate cancer, and CSS can serve as a valuable model for cancer–stroma cell interaction studies." (PMID 40649997, 2025). "PMEPA1 is highly expressed in prostate epithelial cells and is methylated in prostate cancer." (PMID 37628686, 2023). "It is also imperative to investigate the associations of protein levels of AR variants, PMEPA1-b and NEDD4 in prostate cancer tissue samples, which further required to generate the PMEPA1 isoform specific antibodies to distinguish the amino acid sequence differences within N-terminus." (PMID 32842649, 2020). "In androgen independent PC-3 prostate cancer cells, depletion of PMEPA1 gene (isoform -a) facilitated the bone metastasis of xenograft in nude mice through activating TGF-β signaling and subsequent up-regulation of TGF-β responsive pro-metastatic genes including Il11, Adam13 and Mmp9." (PMID 32842649, 2020). "Additionally, increased expression of PMEPA1 in response to decitabine treatment of prostate cancer cells highly suggested that gene methylation contributes to the repression of PMEPA1." (PMID 32842649, 2020). "The pleiotropic nature of PMEPA1 in modulating androgen and TGF-β signaling as well as splice variants mechanisms for functional regulations of cancer-associated genes prompted us to investigate the biological roles of PMEPA1 isoforms in prostate cancer." (PMID 32064040, 2020).
prostate carcinoma (continued). "Therefore, the biomarker candidate features of PMEPA1 isoforms (d and e) were worthwhile being further validated with different prostate cancer cohorts." (PMID 32064040, 2020). "The roles of PMEPA1 individual isoforms in prostate tumor initiation and progression need further clarification for undercover new prostate cancer surveillance and anti- prostate cancer therapy strategy." (PMID 32842649, 2020). "Our findings suggested that alternative splicing events involving PMEPA1 gene contribute to the transcriptional diversity and may be the basis for the multi-functional attributes of PMEPA1 gene in prostate cancer." (PMID 32064040, 2020). "Different from cell growth inhibitory function in context of androgen responsive prostate cancer cells, the PMEPA1 gene (isoform -a and -d) was revealed to promote the growth of non-prostate solid tumors including breast and lung cancers via interrupting TGF-β signaling." (PMID 32842649, 2020). "The promoter methylation of PMEPA1 gene partially contributed to lower expression of PMEPA1-b isoform in prostate cancer cells, which may be helpfully to explain the irregular activation of androgen signaling in prostate tumorigenesis." (PMID 32842649, 2020). "In addition to 4 reported PMEPA1 isoforms (a, b, c and d), one novel isoform PMEPA1-e was identified with RNA Seq analysis of hormone responsive VCaP, LNCaP cells and human prostate cancer samples from The Cancer Genome Atlas (TCGA) dataset." (PMID 32064040, 2020). "The transcript level of PMEPA1-e showed dose-dependent increases in response to androgen treatment in LNCaP cells, consistent with its restricted expression pattern in androgen dependent prostate cancer cells." (PMID 32064040, 2020). "In androgen receptor‐positive prostate cancer cell, PMEPA1 promotes the proliferation." (PMID 30887697, 2019). "The journal retracts the article titled "Analysis of PMEPA1 Isoforms (a and b) as Selective Inhibitors of Androgen and TGF-β Signaling Reveals Distinct Biological and Prognostic Features in Prostate Cancer" [...]." (PMID 41778773, 2026). "Taken together, our findings rendered PMEPA1-e as androgen responsive and PMEPA1-c and PMEPA1-d as TGF-β responsive in prostate cancer cells." (PMID 32064040, 2020). "The transcript levels of PMEPA1-c and PMEPA1-d were detected in both androgen and TGF-β responsive prostate cancer cells." (PMID 32064040, 2020). "Ectopic PMEPA1 (isoform -b) degraded AR protein and decreased expression of AR responsive gene PSA in prostate cancer cells." (PMID 32842649, 2020). "The PMEPA1 isoform c and d were detected in both androgen and TGF-β signaling positive prostate cancer cells although it was only responsive to TGF-β treatment." (PMID 32064040, 2020). "MYC, ATF3, PMEPA1, AURKB, and HMOX-1 were identified as novel targets of curcumin in both less aggressive and highly aggressive metastatic prostate cancer cells in our study." (PMID 31581661, 2019). "The interaction between PMEPA1 and the E3 ubiquitin ligase NEDD4 in prostate cancer cells may play a role in suppressing tumor cell activity." (PMID 39607204, 2024). "It was noted that PMEPA1-e promoted the growth of AR-negative prostate cancer cells in a TGF-β-independent manner while having no impact on AR-positive prostate cancer cells." (PMID 38173834, 2023). "A previous study revealed that PMEPA1 isoforms (a, b, and d) may be a surrogate for androgen and TGF-β signaling in prostate cancer to serve as a biomarker for monitoring disease progression and aggressive clinical outcomes." (PMID 38173834, 2023). "Subsequently, additional three isoforms of PMEPA1 gene were reported with ORF coding for 237 amino acids (PMEPA1-c) in colon and breast cancer, 259 amino acids (PMEPA1-d) in lung cancer and 344 amino acids (PMEPA1-e) in prostate cancer." (PMID 32842649, 2020).
prostate carcinoma (continued). "Recently, our study clarified that PMEPA1-a and PMEPA1-d were PMEPA1 isoforms promoting the cell growth, cell plating efficiency and colony forming capacity in soft agar of AR negative prostate cancer cells." (PMID 32842649, 2020). "Then endogenous androgen signaling in hormone dependent prostate cancer cells resulted in the decreased TGF-β and activated EGF signaling, which could ultimately enhance the expression of PMEPA1 gene." (PMID 32064040, 2020). "Both PMEPA1-d and PMPEA1-e promoted the growth of androgen independent prostate cancer cells." (PMID 32064040, 2020). "Lower PMEPA1-b expression and a higher ratio of PMEPA1-a versus PMEPA-b were all correlated to higher Gleason scores and lower progression free survival rate in the cohort composing of 499 prostate cancer patients." (PMID 32842649, 2020). "Taken together, our study provided new insights into the modulations of AR and TGF-β signaling through understudied isoforms (d and e) of PMEPA1 gene, providing the new understandings of gene networks centering AR/TGF-β signaling regulation in the context of prostate cancer." (PMID 32064040, 2020). "PMEPA1 was also reported as a TGF-β regulated gene in context of both prostate cancer and non-prostate solid tumors including colon, lung and breast cancers." (PMID 32064040, 2020). "As a result of the absence of regulation functions on AR/TGF-β signaling of PMEPA1-c isoform in prostate cancer cells, we focused on the study of clinical significance and relevance of PMEPA1 isoforms (d and e) in prostate cancer patients." (PMID 32064040, 2020). "On the other hand, PMEPA1-d promoted the growth of AR negative prostate cancer cells in TGF-β signaling dependent way." (PMID 32064040, 2020). "The PMEPA1 gene is an important regulator of AR and TGF-β signaling in prostate cancer cells." (PMID 32842649, 2020). "Our lab further identified PMEPA1 isoforms (a, b, and d) with distinct functions to regulate androgen and TGF-β signaling and different expression pattern in androgen-dependent and independent prostate cancer cells (unpublished data)." (PMID 31581661, 2019). "The prostate transmembrane protein, androgen induced 1 (PMEPA1), is another important target gene of TGF-β signaling and highly expressed in many types of cancers including colon, breast, lung and prostate cancer, whereas reports about the expression of PMEPA1 in HCC patients are lacking." (PMID 28230858, 2017). "Our earlier studies defined a mechanistic model for male hormone dependent regulation of AR protein levels in prostate cancer (CaP) cells through a negative feed-back loop between AR and PMEPA1, an androgen induced NEDD4 E3 ubiquitin ligase binding protein." (PMID 25883222, 2015). "PMEPA1 has a growth-promoting or inhibitory role in prostate cancer, depending on whether the cancer cells are negative or positive to androgen receptor (AR)." (PMID 34777336, 2021). "PMEPA1 is a multifunctional protein and has a growth-promoting or inhibitory role in prostate cancer, depending on whether the cancer cells are negative or positive to AR." (PMID 34777336, 2021). "Additionally, it was further revealed that PMEPA1-b isoform as an AR signaling inhibitor and PMEPA1-a has no impact on AR signaling in prostate cancer cells." (PMID 32064040, 2020). "Of note, PMEPA1-c had no impacts on the growth of prostate cancer cells and AR or TGF-β signaling." (PMID 32064040, 2020). "Taken together, PMEPA1 isoforms might function as biomarkers for monitoring disease progression and aggressive clinical outcome via representing surrogate for status of androgen and TGF-β signaling in prostate cancer." (PMID 32842649, 2020). "However, whether other PMEPA1 isoforms (c, d and e) could perturb TGF-β signaling in prostate cancer cells remained unclear." (PMID 32064040, 2020).
prostate carcinoma (continued). "Taken together with the hormone independent growth of PMEPA1-depleted xenograft of LNCaP cells in nude mice, it is implied that the PMEPA-b isoform might contribute to progression into castration resistance stage via manipulating AR signaling in prostate cancer cells." (PMID 32842649, 2020). "Although PMEPA1 was induced by TGF-β, membrane-bound PMEPA1 inhibited TGF-β signaling and prostate cancer bone metastases in a negative feedback loop." (PMID 34827641, 2021). "Several studies including ours showed that PMEPA1-a isoform functioned as TGF-β signaling inhibitor and PMEPA1-b had no impact on TGF-β signaling in prostate cancer and other solid tumors." (PMID 32064040, 2020). "Taken together, our data showed that both AR regulated PMEPA1 isoform e and TGF-β responsive isoforms c and d could not suppress cell growth of hormone responsive prostate cancer cells and interrupt androgen signaling." (PMID 32064040, 2020). "As for PMEPA1, some studies have shown PMEAP1 inhibited proliferation through androgen receptor, however, androgen receptor and the related signalling pathways have been activated in prostate cancer, but maybe not in lung cancer or breast, or colorectal cancer." (PMID 30887697, 2019).